FABP4 (fatty acid binding protein 4)
Diseases named in the same sentence as FABP4 in open-access papers (continued):
Sharing a sentence is not in itself a finding about the gene and the disease.
Insulin resistance (continued). "Here, we examined the relationships between adiposity and insulin resistance and circulating levels of adiponectin, FABP4, lipocalin-2, PAI-1 and FGF21 before and after high fat overfeeding for 28 days." (PMID 24205333, 2013). "We also observed relationships between serum FABP4 and numerous measures of adiposity and insulin resistance at baseline." (PMID 24205333, 2013). "Circulating FABP4 appears to be a useful biomarker for detecting pre-clinical stage of metabolic syndrome, especially insulin resistance, in the general population." (PMID 24278421, 2013). "In the present study, we confirmed that FABP4 levels were significantly correlated with adiposity, blood pressure, insulin resistance, and dyslipidemia in HD patients." (PMID 22102888, 2011). "In this study, we show that FABP4 plasma levels are significantly higher in obese children and correlate with measures of insulin resistance and systemic inflammation, such as HOMA and hsCRP, respectively." (PMID 20156355, 2010). "Small molecules that inhibit FABP4 mediated responses, might serve as potential candidates for the treatment of different components of metabolic syndromes, such as insulin resistance, type 2 diabetes, and atherosclerosis." (PMID 40002815, 2025). "Finally, FABP4 and FAPB5 (Fatty acid-binding protein 4 and 5) are associated with inflammation, liver fibrosis and insulin resistance." (PMID 39746606, 2025). "Also, it has been shown that the serum FABP4 is associated with myocardial neutral lipid content in patients with type 2 diabetes mellitus (T2DM), where FABP4 has been found to induce insulin resistance by increasing the intracellular lipid contents." (PMID 38731797, 2024). "Another study indicated that propionate intake could increase the secretion of glucagon and fatty acid-binding protein 4 (FABP4) in both mice and humans, potentially leading to insulin resistance." (PMID 38411058, 2024). "Consequently, less insulin resistance suggested a reduction of lipolysis and circulating FABP4 levels in patients after 6 months treatment." (PMID 38172989, 2024). "Additionally, the distribution of adipose tissue, genetic variability, insulin resistance, and inflammation all contribute to the complex interplay of FABP-4 in CDs." (PMID 38024104, 2023). "We hypothesized that higher FABP-4 could be positively associated with CRC risk, either directly, by facilitating fatty acid supply for tumor growth, or indirectly through FABP-4-related enhancement of inflammation and insulin resistance." (PMID 37833736, 2023). "Multiple effects mediated by FABP4, such as insulin resistance, promote BE carcinogenesis." (PMID 35654816, 2022). "Additionally, the FABP4 gene expression has been found to be upregulated in the livers of morbidly obese patients in the context of insulin resistance and in patients with different MAFLD severities." (PMID 35052876, 2022). "Pharmacological blockade of FABP4 with small molecule inhibitors such as BMS309403 have shown to be an effective therapeutic strategy against insulin resistance, diabetes mellitus, and atherosclerosis by suppressing the associated inflammatory and apoptotic processes." (PMID 35955575, 2022). "Studies have shown that FABP4‐deficient mice have protective effects on dyslipidemia, hyperglycemia, and insulin resistance, and interference with FABP4 can promote mitochondrial maintenance of high membrane potential, which is conducive to strengthening mitochondrial function." (PMID 35088483, 2022). "FABP4 is thought to play an important role in insulin resistance in T2DM." (PMID 36532833, 2022). "FABP4 plays an important role in the development of insulin resistance and atherosclerosis, and its increase in blood levels may be associated in humans with obesity, diabetes, hypertension, and cardiovascular diseases." (PMID 35892532, 2022). "We further provided evidence that higher FABP4 concentrations early in pregnancy may indicate subsequent higher insulin resistance levels." (PMID 34368366, 2021).
Insulin resistance (continued). "We previously showed in experimental models that inhibition of FABP4 by a small molecule might be a novel therapeutic strategy against insulin resistance, type 2 diabetes mellitus and atherosclerosis." (PMID 33597568, 2021). "FABP-4 also contributes to insulin resistance by accumulating short-chain-free fatty acids." (PMID 34217172, 2021). "Moreover, Crtc1–/– mice were more prone to insulin resistance and dyslipidemia, as evidenced by higher levels of plasma glucose, insulin and FABP4 than wildtype mice." (PMID 33912553, 2021). "In animal models, it was found that FABP4 inhibitors ameliorate insulin resistance, diabetes mellitus, fatty liver disease, and atherosclerosis, implying that inhibition of FABP4 may be a therapeutic strategy for metabolic syndrome." (PMID 34944525, 2021). "Furthermore, it has been reported that neutralization of secreted FABP4 with an antibody to FABP4 can be a novel strategy for treatment of insulin resistance, type 2 diabetes mellitus, atherosclerosis and vascular injury." (PMID 33597568, 2021). "Serum FABP4 levels may result in insulin resistance, which in turn may lead to a compensatory increase in insulin secretion trying to maintain glucose homeostasis." (PMID 34174950, 2021). "The similar association between FABP4 an FLI in the different populations might be due to the fact that metabolic patients share common characteristics, such as insulin resistance." (PMID 34966292, 2021). "Thus, increased FABP-4 leads to the development of insulin resistance as a consequence of defective insulin secretion." (PMID 34217172, 2021). "Recent studies have also demonstrated that neutralization of secreted FABP4 with an antibody to FABP4 could be a feasible approach for treatment of insulin resistance, type 2 diabetes mellitus, vascular injury and atherosclerosis." (PMID 32539832, 2020). "Pro-inflammatory factors, such as leptin, tumor necrosis factor α (TNF-α), monocyte chemoattractant protein 1 (MCP-1), resistin, and FABP4, are elevated, while anti-inflammatory factors, e.g., adiponectin, are low, in chronic systemic inflammation, promoting insulin resistance and atherosclerosis." (PMID 32856199, 2020). "Adipose tissue of obese patients undergoes uncontrolled lipolysis as a consequence of insulin resistance, which might explain the high plasma levels of FABP4 observed in obese patients." (PMID 32856199, 2020). "On the other hand, a sr1054135 polymorphism associated with high plasma levels of FABP4 in both obese and non-obese patients correlates with increased risk of insulin resistance and systemic inflammation." (PMID 32856199, 2020). "Obese mice deficient for both FABP4 and 5 exhibited reduced tissue fatty-acid composition and did not develop insulin resistance." (PMID 33105856, 2020). "Chemical inhibition of FABP4 by a small molecule inhibitor could be a novel therapeutic strategy against insulin resistance, diabetes mellitus and atherosclerosis." (PMID 32539832, 2020). "FABP4 is a cytoplasmic fatty acid chaperone clearly engaged in the onset of insulin resistance." (PMID 30857223, 2019). "FABP4 is strongly involved in glucose and lipid metabolism, inflammation, and insulin resistance." (PMID 30857223, 2019). "FABP4 was also detected in apoptotic granulosa cells in atretic antral follicles of the mouse ovary, which suggests a potential link to polycystic ovary syndrome (PCOS), which is known to be frequently associated with insulin resistance." (PMID 30857223, 2019). "FABP4 represents an important molecule dealing with insulin resistance in T2DM." (PMID 30857223, 2019). "A specific FABP4 inhibitor BMS309403 can effectively protect against diabetes mellitus, insulin resistance, and atherosclerosis in mouse model, which suggests that chemical inhibitors of FABP4 may become an effective therapeutic strategy." (PMID 30142969, 2018). "Moreover, high expression of FABP4 in adipose tissue has been suggested to increase insulin resistance." (PMID 30453990, 2018).
Insulin resistance (continued). "Furthermore, the roles of FABP4 in the development of adiposity, insulin resistance, T2DM, atherosclerosis, hypertension, coronary artery and cerebrovascular diseases, as well as metabolic syndrome, are of great concern." (PMID 30513800, 2018). "According to another report, hyperinsulinemia and insulin resistance in the context of both dietary and genetic obesity improved in FABP4 deficient mice, but the effect of FABP4 on insulin sensitivity was not seen in lean mice." (PMID 28654680, 2017). "In conclusion, our study suggests indicates that FABP4 may not only be an effective marker of insulin resistance in skeletal muscle, but also enhances insulin secretion." (PMID 28654680, 2017). "We previously demonstrated that the use of a small molecule FABP4-specific inhibitor might be a novel therapeutic strategy against insulin resistance, type 2 diabetes mellitus and atherosclerosis." (PMID 27124282, 2016). "In obese mice, FABP4 deletion improved insulin resistance and lipid metabolic disorders." (PMID 26752184, 2016). "It has also been demonstrated in experimental models that chemical inhibition of FABP4 could be a therapeutic strategy against insulin resistance, diabetes mellitus, fatty liver disease and atherosclerosis." (PMID 25142635, 2014). "Indeed, these researchers demonstrated that the chemical inhibition of the function of FABP4 prevents the insulin resistance and atherosclerosis induced by a high-fat diet in mice." (PMID 24603714, 2014). "This indicates that TNFα may be a crucial mediator of inflammation in WAT and whole-body insulin resistance of Crif1f/+,Fabp4 mice." (PMID 23516375, 2013). "Moreover, FABP4 disruption decreases insulin resistance, dyslipidemia and liver steatosis in obese or fat fed animals." (PMID 24205333, 2013). "Hence, we next focused on the significance of FABP4 in metabolic disorders, especially insulin resistance, in the study subjects." (PMID 24278421, 2013). "It has also been demonstrated that chemical inhibition of FABP4 could be a therapeutic strategy against insulin resistance, diabetes mellitus, fatty liver disease, and atherosclerosis in experimental models." (PMID 24278421, 2013). "To determine whether macrophages in the adipose tissue of Crif1f/+,Fabp4 mice play a role in insulin resistance, we depleted macrophages from adipose tissue by intraperitoneal treatment with clodronate liposomes." (PMID 23516375, 2013). "Previous studies using animal models indicated that FABP4 plays a significant role in several aspects of metabolic syndrome, including insulin resistance, type 2 diabetes, and atherosclerosis, through its action at the interface of metabolic and inflammatory pathways in adipocytes and macrophages." (PMID 24278421, 2013). "Our findings suggest that high levels of FABP4 in the plasma are not just a clinical manifestation of insulin resistance but also a causative factor of the development of insulin resistance at the vascular level leading to NO metabolism alteration." (PMID 22709426, 2012). "We also found an increased liver expression of FABP4 in MO-IR patients, suggesting that adipose tissue and liver may act in a balanced manner according to the insulin resistance status." (PMID 23139800, 2012). "Insulin resistance emerged as an important determinant of FABP4 adipose expression." (PMID 23139800, 2012). "Previous studies using animal models indicate that FABP4 plays a significant role in several aspects of metabolic syndrome, including insulin resistance, type 2 DM and atherosclerosis, through its action at the interface of metabolic and inflammatory pathways in adipocytes and macrophages." (PMID 22102888, 2011). "We previously demonstrated that chemical inhibition of FABP4 could be a therapeutic strategy against insulin resistance, diabetes mellitus, fatty liver disease, and atherosclerosis in experimental models using one of the specific FABP4 inhibitors, BMS309403." (PMID 22121495, 2011).
Insulin resistance (continued). "Serum levels of FABP4 were significantly increased in overweight and obese subjects compared to the level in lean controls and were positively correlated with waist circumference, blood pressure, and insulin resistance." (PMID 22121495, 2011). "In fact, we recently demonstrated that chemical inhibition of FABP4 could be a therapeutic strategy against insulin resistance, diabetes mellitus (DM), fatty liver disease, and atherosclerosis in experimental models." (PMID 22102888, 2011). "However, a synthetic inhibitor for the related protein FABP4 has been developed and was shown to improve insulin resistance and atherosclerosis in mice." (PMID 20847935, 2010). "The analysis revealed a significant and positive association between FABP4 and HbA1c (r = 0.126, p < 0.001), fasting blood glucose (FBG) (r = 0.184, p < 0.001), fasting insulin (r = 0.326, p < 0.001), and the homeostatic model of insulin resistance (HOMA-IR) (r = 0.333, p < 0.001)." (PMID 38731797, 2024). "Thus, acute treatment with GLP-1 in fat tissue with insulin resistance might enhance lipolysis and consequently, increase circulating FABP4." (PMID 38172989, 2024). "Additionally, the mRNA expression of Fabp4, an intracellular lipid-binding protein most abundantly expressed in adipocytes and macrophages, was upregulated in the livers of morbidly obese patients with insulin resistance." (PMID 39519077, 2024). "Additionally, inhibiting FABP4 secretion might also be a novel therapeutic strategy to prevent insulin resistance and type 2 diabetes." (PMID 35563118, 2022). "Elevated FABP4 concentrations may impair the ability of adipocytes to take up and retain free fatty acids, resulting in ectopic lipid accumulation, a critical contributing factor to insulin resistance, type 2 diabetes, and GDM." (PMID 34368366, 2021). "FABP4 is secreted from adipocytes via a non-classical secretion pathway in association with lipolysis despite the lack of signal peptides and acts as an adipokine for the development of insulin resistance, atherosclerosis and vascular remodeling." (PMID 32539832, 2020). "Thus, the elevated levels of circulating FABP4 in obese individuals could induce hyperglycemia and hyperinsulinemia promoting insulin resistance and the development of type 2 diabetes." (PMID 32856199, 2020). "Therefore, our findings confirmed the hypothesis that plasma FABP4 level can serve as a biomarker of insulin resistance or metabolic syndrome." (PMID 29335416, 2018). "It was already confirmed that in the non-gestational population, FABP4 is an independent risk factor, not only for not metabolic syndrome but also its related indexes, including waist circumference, blood pressure, dyslipidemia, and insulin resistance." (PMID 29394285, 2018). "Furthermore, FABP4 has been demonstrated to act as an adipokine for the development of insulin resistance in liver, suppression of cardiomyocyte contraction, inhibition of endothelial nitric oxide synthase in endothelial cells and proliferation and migration of vascular smooth muscle cells." (PMID 26754658, 2016). "Indeed, deletion of FABP4/aP2 leads to embryonic lethality whilst diminished FABP4/aP4 gene expression has been shown to protect animals from multiple metabolic syndromes including obesity, insulin resistance, hepatosteatosis and atherosclerosis." (PMID 25822632, 2015). "FABP4 has been positively associated with conditions that could increase the risk of SCD including coronary artery disease, metabolic syndrome, overall insulin resistance, and incident diabetes." (PMID 24455402, 2013). "For example, propionate elevates plasma levels of norepinephrine, fatty acid-binding protein 4 (FABP4), and glucagon, stimulating hyperglycemia and glycogenolysis, which can lead to compensatory hyperinsulinemia and insulin resistance." (PMID 40395507, 2025).
Insulin resistance (continued). "Serum FABP4 levels are negatively correlated with glucose disposal rate (GDR), a marker of insulin resistance in skeletal muscle, as well as with serum insulin levels." (PMID 40002815, 2025). "Moreover, endothelial FABP4 promotion of lipolysis-mediated insulin secretion may be detrimental for β cell health and function, since hyperinsulinemia is a driver for the development of insulin resistance." (PMID 37279064, 2023). "Nevertheless, the enhanced lipolysis associated with insulin resistance may contribute to increased FABP4 secretion from adipocytes, which in turn would contribute to further activation of HSL, promoting a vicious cycle that would lead to increase levels of circulating FABP4." (PMID 35052876, 2022). "Therefore, we can also speculate that insulin resistance occurs when FABP4 levels are high." (PMID 36060264, 2022). "FABP4 plays a crucial role in the regulation of glucose/lipid metabolism and insulin sensitivity: FABP4-null mice are protected from HFD-induced hyperglycaemia, hyperinsulinaemia, and insulin resistance." (PMID 35628332, 2022). "Fatty acid-binding protein-4 (FABP-4) is a novel adipokine, which is expressed in adipocytes and plays a part in the initiative mechanism of insulin resistance and type 2 DM via suppressing PPAR gamma." (PMID 34217172, 2021). "The results showed that DCI played a pivotal role in the hepatocellular insulin resistance of PA through the IRS-2-PI3K/AKT pathway and that PTP1B, XBP1S, SREBP-1c, FABP4, G6Pase, Pepck and other genes were potential sites in dietary supplements." (PMID 34335474, 2021). "FABP4, known as adipocyte FABP (A-FABP) or aP2, is expressed in both adipocytes and macrophages and contributes to the development of insulin resistance and atherosclerosis." (PMID 33143633, 2020). "Dual ablation of FABP4 and FABP5 was shown to protect from metabolic disorders including insulin resistance, fatty liver, and atherosclerosis more than does a single deficiency of FABP4 or that of FABP5 in mouse models." (PMID 33071982, 2020). "Furthermore, clinical research also suggested that FABP4 played critical roles in macrophage cholesterol trafficking and inflammation, and may promote the obesity development, insulin resistance, metabolic syndrome, diabetes, gestational diabetes mellitus, hypertension and atherosclerosis." (PMID 30969942, 2019). "More importantly, FABP4 has been shown to have pleiotropic effects in steatosis, NAFLD, insulin resistance and metabolic syndrome as well as in cell differentiation and chronic inflammation through macrophage activation." (PMID 31874999, 2019). "There is ample evidence to suggest a link between fatty acid-binding protein 4 (FABP4) and insulin resistance, GDM, and T2DM." (PMID 30857223, 2019). "Our study shows that circulating FABP4 concentrations are negatively correlated with both GDR, which is a marker of insulin resistance in skeletal muscle, and serum blood insulin levels (IRI) following a MTT in individuals with T2DM." (PMID 28654680, 2017). "Fatty acid-binding protein 4 (FABP4) and FABP5 are expressed in both adipocytes and macrophages and play significant roles in the development of insulin resistance and atherosclerosis." (PMID 28303004, 2017). "In another study, ablation of adipocyte/macrophage lipid chaperones aP2 (FABP4) and mal1 (FABP5) increased adipose DNL which protected mice from diet-induced obesity, fatty liver disease and insulin resistance." (PMID 26752997, 2016). "In atretic antral follicles of the mouse ovary, FABP4 was detected in apoptotic granulosa cells, suggesting a possible relevance to polycystic ovary syndrome (PCOS), which often coexists with insulin resistance." (PMID 22121495, 2011). "For instance, elevated circulating levels of fatty acid-binding protein 4 (FABP4) and glutathione peroxidase 3 (GPX3) were associated with declining insulin secretion, independent of insulin resistance." (PMID 40768044, 2025).